LINC01111 (long independently transcribed non-coding RNA 1111)
Gene: Long non-coding RNA gene on chromosome 8 (76,406,654 to 76,524,356, forward strand). Ensembl gene ENSG00000254300.
Diseases named in the same sentence as LINC01111 in open-access papers:
LINC01111 is named in the same sentence as 2 diseases in open-access papers, as found by Europe PMC text mining. Sharing a sentence is not in itself a finding about the gene and the disease. The quoted sentences say what the papers report.
pancreatic cancer (1 paper, 2021). "LINC01111, identified as an oncosuppressor in pancreatic cancer, and the annotated LHX1-DT and AC006387.1 transcripts were also significantly enriched in the DA population." (PMID 33445654, 2021).
tumor (3 papers, 2019 to 2023). "Furthermore, ISH analyses revealed significant downregulation of LINC01111 expression in 95 paired paraffin-embedded PC surgical specimens and that a low level of LINC01111 was associated with poor prognosis of PC patients, indicating that LINC01111 acts as a tumor suppressor in PC." (PMID 31767833, 2019). "LINC01111 has been found to be downregulated in tissue and plasma samples of patients with PCa; in addition, it plays a role in tumor suppression and has been positively correlated with the survival of PCa patients." (PMID 37189687, 2023). "To gain a better understanding of the molecular mechanism by which LINC01111 exerted its tumor suppressive function in PC cells, we performed mRNA microarray analysis to analyze the effects of LINC01111 overexpression on the gene expression profile." (PMID 31767833, 2019). "Therefore, the effect of LINC01111 on PC initiation and progression can be partly explained with a ceRNA mechanism, through which LINC01111 functions as a tumor suppressor." (PMID 31767833, 2019). "On the other hand, LINC01111, LINC01963, DGCR5, MEG3, GAS5, and LINC00261 are among tumor suppressor lncRNAs in this tissue." (PMID 34827663, 2021). "Significant downregulation of LINC01111 was observed in PC tumor tissues compared with adjacent normal tissues." (PMID 31767833, 2019). "In the present study, we demonstrated that LINC01111 expression levels are clearly decreased and that the SAPK/JNK signaling pathway is significantly activated by the downregulation of DUSP1 protein in PC, which promotes tumorigenesis and tumor metastasis." (PMID 31767833, 2019).